H19 (H19 imprinted maternally expressed transcript)
Diseases named in the same sentence as H19 in open-access papers (continued):
Sharing a sentence is not in itself a finding about the gene and the disease.
colon carcinoma (40 papers, 2011 to 2025). "LncRNA H19 is upregulated in colon cancer and associated with a poor prognosis." (PMID 38785973, 2024). "We confirmed that the overexpression of H19 not only posed a risk factor for reducing the survival in patients with colon cancer but was also associated with the cell proliferation and metastasis of colon cancer cells." (PMID 39202109, 2024). "Another study published this year linked H19 overexpression to colon cancer recurrence." (PMID 36127676, 2022). "Similarly, elevated expression of H19 lncRNA in cells isolated from metastases due to promoter demethylation was associated with poor survival of colon cancer patients." (PMID 31623387, 2019). "H19 rs2839698 variant showed a statistically significant association under the dominant model (p = 0.029, unadjusted OR = 0.18, 95% CI: 0.02–0.81), indicating a substantially lower frequency of the minor allele among rectal tumor cases compared to colon tumors." (PMID 41463069, 2025). "Knockdown of H19 sensitized colon cancer cells to 5-Fu resistance, while enhancing H19 expression improved 5-Fu resistance." (PMID 39830506, 2024). "In particular, we provided evidence for the first time that HDACi ITF2357 is efficacious in a colon cancer model by upregulating lncH19 and is capable of overcoming 5-FU resistance in highly H19-expressing CRC cells." (PMID 37841928, 2023). "For example, a report from a few years ago showed that H19 promoted the transformation process of colon cancer epithelial cells into mesenchymal cells through the H19/Mir-29B-3p/PGRN Axis." (PMID 36127676, 2022). "In colon cancer, lncRNA H19 competitively combined with miR-138 and miR-200a, up-regulating the expression of key genes in EMT (VIM, ZEB1, and ZEB2), and promoting the progress of EMT." (PMID 35094653, 2022). "At the same time, we found that the expression of H19 affects the content of B cells and macrophages in the microenvironment of colon cancer and affects the prognosis of colon cancer." (PMID 34922547, 2021). "Previous works have reported a protagonist role for the lncRNA H19 as protagonist in regulating various cancer-related mRNAs in colon cancer and in CRC in general." (PMID 34178670, 2021). "This study helps to inform clinical decisions and understand the role of H19 in colon cancer while providing potential biomarkers for targeted treatment of colon cancer." (PMID 34922547, 2021). "To explore the regulatory mechanism of H19 in colon cancer, we constructed H19-miRNA-mRNA based on the lncRNA competitive endogenous RNA mechanism." (PMID 34922547, 2021). "To further study the role of H19 in colon cancer, we analyzed the expression levels of H19 in 32 cancers using the TIMER database." (PMID 34922547, 2021). "For example, overexpression of H19 decreases overall survival and increases the migration of colon cancer cells." (PMID 32883200, 2020). "LncRNA H19 is upregulated in colon cancer tissues, and its knockdown represses the migratory and invasive ability of colon cancer cells via sponging miR-138 and promoting the subsequent upregulation of high-mobility group A (HMGA1)." (PMID 33246471, 2020). "The read count data of normal colon tissues (n = 41) and colon tumour tissues (n = 285) downloaded from the GDC database also indicated the up‐regulation of H19 expression in malignant colon tissues." (PMID 30920116, 2019). "The authors implicated the H19-miR-138-HMGA1 pathway in regulating the migration and invasion of colon cancer." (PMID 31623387, 2019). "It was also proven that H19 and miR-675 (processed form of the former) were found to be upregulated in human colon cancer, both in cell lines and primary CRC biopsies, compared to adjacent noncancerous tissues." (PMID 31623387, 2019). "Among them, lncRNA H19 was up‐regulated in colon tumours and correlated with poor patient prognosis." (PMID 30920116, 2019).
colon carcinoma (continued). "We measured H19 expression using qRT-PCR and analysed the effects of H19 on colon cancer cell proliferation via cell growth curve, cell viability assay, and colony formation assays." (PMID 28164117, 2017). "H19 overexpression facilitated colon cancer cell proliferation, whereas H19 knockdown inhibited cell proliferation." (PMID 28164117, 2017). "The 3′-UTR of RB mRNA aligns with the sequence of mature miR-675, and the level of RB protein also appears to be negatively correlated with the levels of both H19 and miR-675 in human colon cancer cells." (PMID 26637808, 2016). "The 3′-UTR of RB mRNA aligned with the sequence of mature miR-675 and the level of RB protein also appears to be negatively correlated with the levels of both H19 and miR-675 in the human colon cancer cells." (PMID 26637808, 2016). "To further confirm the relationship between H19 expression and colon cancer progression, we compared the H19 expression level in colon cancer and normal tissues using public database Oncomine." (PMID 26068968, 2015). "H19 RNA has been characterized as an oncogenic long non-coding RNA (lncRNA) in breast and colon cancer." (PMID 24466011, 2014). "LncRNAs have been reported to be involved in cancer development in three different ways: Firstly, some lncRNAs take part in the process as oncogene or oncogene regulator, for example, MALAT1 gene in non-small cell lung cancer and H19 in colon cancer." (PMID 24330491, 2013). "In detail, HDAC2 was demonstrated to inhibit H19 expression in colon carcinoma." (PMID 40885718, 2025). "Conversely, in colon carcinoma, H19 promotes EMT via binding to hnRNPA2B1." (PMID 40885718, 2025). "We consider these results relevant since they imply that lncH19 can be exploited to favor apoptosis induction and that HDACi may promote a H19-dependent targeted effect in colon cancer cells." (PMID 37841928, 2023). "This evidence indicates that H19 is involved in the process of colon cancer and may be an important biomarker." (PMID 34922547, 2021). "Next, we analyzed each lncRNA and found that the expression of H19 was significantly related to the T stage, N stage, M stage and TNM stage of colon cancer, which suggested that high expression of H19 may be involved in the progression of colon cancer." (PMID 34922547, 2021). "However, the expression of H19 was significantly related to the tumor invasion depth of colon cancer (T, p < 0.05), distant metastasis (M, p < 0.01), lymphatic node metastasis (N, p < 0.001) and TNM stage (p < 0.001)." (PMID 34922547, 2021). "Further analysis revealed that the expression of H19 may macrophage invasion and lead to poor prognosis of colon cancer, and high expression of H19 may lead to tumor cell resistance by regulating CDDN1." (PMID 34922547, 2021). "High expression of H19 leading to antitumor drug resistance has been observed in colon cancer." (PMID 34922547, 2021). "Indeed, H19 promotes the migration and invasion of colon cancer cells via the MAPK signaling pathway and those of human osteosarcoma through the NF-κB pathway." (PMID 32610610, 2020). "Notably, H19 overexpression stimulates resistance to 1,25(OH)2D3 treatment in colon cancer cells and mouse models." (PMID 33246471, 2020). "H19 expression is significantly up-regulated in immunodeficient mice induced by colon cancer cells, and H19 may be taken as a novel therapeutic target in colon cancer." (PMID 32117736, 2020). "Among them, lncRNA H19 was upregulated in colon tumors and correlated with poor patient prognosis." (PMID 31623387, 2019). "Our findings unveil that SIRT1 dependent autophagy pathway could affect 5-Fu chemoresistance in colon cancer cells, which was modulated by H19/miR-194-5p axis." (PMID 30451820, 2018). "In this regard, H19 and its derived miR-675 may be tumor promoters in gastrointestinal cancers like gastric caner and colon cancer." (PMID 28212565, 2017).
colon carcinoma (continued). "To explore the biological importance of H19 in tumorigenesis, we examined the effect of H19 in regulating the capacity of colony formation in two colon cancer cells HCT-116 and SW620 because anchorage independent growth is an important characteristic for malignancy and EMT." (PMID 26068968, 2015). "Herein, H19 was identified to be significantly upregulated in mesenchymal-like colon cancer cells." (PMID 26068968, 2015). "Finally, clinical studies presented upregulation of H19 in colon cancer tissues when compared with adjacent normal tissues." (PMID 26068968, 2015). "In colon cancer H19 was shown to be directly activated by the oncogenic transcription factor c-Myc, suggesting H19 may be an intermediate functionary between c-Myc and downstream gene expression." (PMID 21489289, 2011). "This indicates that H19 expression may be related to the development and prognosis of colon cancer." (PMID 34922547, 2021). "H19 may be a biomarker for targeted treatment of colon cancer." (PMID 34922547, 2021). "H19 directly binds to hnRNPA2/B1 and afterward initiates the ERK signaling pathway, which orchestrates an EMT in colon cancer cells." (PMID 38785973, 2024). "High mobility group AT-hook 1 (HMGA1) is inhibited by H19 short hairpin RNA (shRNA) and is promoted by miR-138 inhibitor, and the H19-miR138-HMGA1 pathway plays important roles in mediating the invasion and migration of colon cancer." (PMID 32117736, 2020). "H19 can suppress vitamin D receptor (VDR) expression via miR-675-5p, and increased H19 leads to the resistance to 1,25(OH)2D3 treatment in the advanced colon cancer." (PMID 32117736, 2020). "To elucidate the function of H19 in EMT, we performed the gain-of-function analysis using retroviral transduction of H19 in human colon cancer cells HT-29 and SW620." (PMID 26068968, 2015). "It was found that The H19/miR-194-5p axis regulates the SIRT1-dependent autophagy pathway, which may impact 5-Fu chemoresistance in colon cancer cells." (PMID 39830506, 2024). "Six of nine data sets, which include microarray expression profiles classified into normal or colon cancer tissues, displayed higher H19 expression levels in colon cancer tissues rather than normal tissues." (PMID 26068968, 2015). "Later, we found that H19 was significantly overexpressed in gastrointestinal tumors based on the TIMER database and that H19 expression was related to B-cell and macrophage infiltration and may be involved in the poor prognosis of colon cancer." (PMID 34922547, 2021).
endometriosis (39 papers, 2014 to 2025). The growth of functional endometrial tissue in anatomic sites outside the uterine body. "On the other hand, the H19 gene has been implicated in the development of several disorders, including endometriosis and various malignancies 35-37." (PMID 39898248, 2025). "In the microenvironment level, another research group reported the importance of the H19/miR-342-3p/IER3 pathway in reducing the risk of endometriosis through suppressing Th17 cell differentiation." (PMID 40792071, 2025). "H19 has been linked to several reproduction-related diseases, such as endometriosis, diminished ovarian reserve (DOR), polycystic ovary syndrome (PCOS), uterine fibroids (UFs), and male factor infertility." (PMID 37507391, 2023). "H19 overexpression in endometriosis lesions is associated with infertility, relapse, bilateral ovarian lesions, elevated CA125 levels, and progression in the altered stage of the American Fertility Society disease (rAFS)." (PMID 36232884, 2022). "The study aimed to analyze the expression of four long non-coding RNA (lncRNA) genes, UCA1, MALAT1, TC0101441, and H19, in the context of the risk of developing endometriosis." (PMID 36232884, 2022). "An association was observed between H19 gene expression and rASRM classification in the endometriosis group." (PMID 36232884, 2022). "Overexpression of H19 lncRNA in endometriosis lesions was associated with infertility, recurrence of disease, bilateral ovarian lesions, an increased CA125 level and with progression in the revised American Fertility Society (rAFS) disease stage." (PMID 34768856, 2021). "Furthermore, among endometriosis patients, there was an association between H19 expression and the rAFS score for reproductive medicine classification of endometriosis (rASRM) score." (PMID 38166752, 2024). "A statistically significant association was found between H19 gene expression in relation to The Revised American Society for Reproductive Medicine classification of endometriosis (rASRM) in the group of patients with endometriosis." (PMID 36232884, 2022). "In the first reported example of sponging in endometriosis, decreased levels of the H19 lncRNA was shown to be associated with an increase in let-7 miRNA activity, which inhibits IGF1R expression resulting in the reduced proliferation of endometrial stroma cells." (PMID 34768856, 2021). "A transcriptomic analysis revealed key miRNAs and lnCRNA implicated in endometriosis and RIF, including miR-9, miR-34, and miR-135a/b miR-30d-5p, PART1, MIR17HG, H19, LINC00173, NEAT1, and LINC01960-201." (PMID 39858500, 2025). "For example, ACTA2 gene expression is increased by lncRNA H19 which sponges to miR-216a-5p to mediate stromal cell invasion and migration in endometriosis and alters stromal cell growth." (PMID 40457415, 2025). "The first documented case of sponging in endometriosis demonstrated a correlation between decreased levels of H19 lncRNA and increased activity of let-7 miRNA." (PMID 41301870, 2025). "In vivo investigations using a nude mouse model have demonstrated that silencing of H19 leads to a significant decrease in endometriosis." (PMID 38166752, 2024). "Studies have shown that H19 expression is extinguished in mononuclear cells obtained from the peritoneal fluid of endometriosis patients." (PMID 38791310, 2024). "Based on these findings, it can be concluded that 17β-estradiol is involved in the development of endometriosis through the regulation of H19." (PMID 38166752, 2024). "The work of scientists from Iran has shown that the expression of the VEGF, IGF1, IGF2 and H19 lncRNA genes and the epigenetic changes of H19 lncRNA play a dynamic role in the pathogenesis of endometriosis." (PMID 38791310, 2024). "Our previous study showed that lncRNA H19 expression was elevated in the eutopic endometrium of patients with endometriosis." (PMID 38744310, 2024).
endometriosis (continued). "Our preliminary results and the results of others have shown that lncRNA H19 expression is elevated in both eutopic endometrium and ectopic endometriosis tissue." (PMID 38744310, 2024). "H19 levels were found to be increased in both the eutopic endometrium and ectopic endometrium of the endometriosis model, observations that are consistent with our previous findings in human tissues." (PMID 38744310, 2024). "The development of endometriosis is possible through the action of H19, which modulates the EMT process." (PMID 38791310, 2024). "Decreased expression of lncRNA H19 promoted endometriosis in women via downregulation of IGF signalling via H19/Let-7/IGF1R axis." (PMID 40176927, 2024). "17β-estradiol is known to play a role in regulating H19 expression and function in endometriosis patients." (PMID 38791310, 2024). "Meanwhile, increased lncRNA H19 expression has been reported in the ectopic endometrium of patients with endometriosis." (PMID 38744310, 2024). "This approach yielded a special function of H19, highlighting its potential as a therapeutic target for endometriosis." (PMID 38744310, 2024). "An estrogen-regulated lncRNA H19/miR-216a-5p axis has been described in women with endometriosis, and an increased expression of miR-216a enhanced endometrial cell invasion and migration." (PMID 38666942, 2024). "The results of some studies have shown reduced H19 expression in endometriosis patients to be correlated with reduced levels of IGF1R mRNA in the eutopic endometrium compared to women without endometriosis." (PMID 38791310, 2024). "It was found that the expression of H19 was significantly suppressed in mononuclear cells obtained from peritoneal fluid of patients with endometriosis." (PMID 38166752, 2024). "Based on these findings, it can be concluded that H19 promotes endometriosis by modulating the EMT process." (PMID 38166752, 2024). "Previous studies from our group and others have shown increased IncRNA H19 expression in both the eutopic endometrium and the ectopic endometriosis tissue during endometriosis." (PMID 38744310, 2024). "The role of H19 in endometriosis, as revealed by both clinical and basic studies, presents contradictory data, highlighting the need for additional confirmation." (PMID 38166752, 2024). "It has been observed that 17β-estradiol plays a role in regulating the expression pattern and function of H19 in patients with endometriosis." (PMID 38166752, 2024). "In vivo studies have shown that the knockdown of lncRNA H19 inhibits endometriosis in naked mice.lncRNA H19, which acts as a molecular sponge, reduces the bioavailability of let-7 microRNAs." (PMID 38791310, 2024). "The results presented in this study concerning the analysis of VEGF, IGF1/2 and H19 genes show the presence of certain dependencies of their expression with endometriosis." (PMID 38791310, 2024). "H19 is involved in the pathogenesis of endometriosis by modulating the proliferation and invasion of ectopic endometrial cells." (PMID 38791310, 2024). "The present study identifies that highly expressed H19 leads to increased aerobic glycolysis and histone lactylation levels in endometriosis." (PMID 38744310, 2024). "The aim of the study was to analyze the expression levels of the VEGF, IGF1/2 and H19 genes in patients with endometriosis and in the control group." (PMID 38791310, 2024). "It has been reported that H19 can stimulate the formation of fibrotic tissue in women suffering from endometriosis through the H19/miR-216a-5p/ACTA2 pathway." (PMID 38166752, 2024). "In in vivo experiments on naked mice, H19 silencing led to a significant reduction in the incidence of endometriosis." (PMID 38791310, 2024). "Taken together, the results of our study demonstrate that high expression of H19 in endometriosis promotes enhanced levels of aerobic glycolysis and histone lactylation." (PMID 38744310, 2024).